LEP (leptin)
Diseases named in the same sentence as LEP in open-access papers (continued):
Sharing a sentence is not in itself a finding about the gene and the disease.
Obesity (continued). "Leptin may thus contribute to CB dysfunction and increased sympathetic activity seen is obesity and obesity-related syndromes, as OSA and metabolic syndrome (see e.g.)." (PMID 33353562, 2020). "According to the literature, higher leptin levels were found in women than in men, and the presence of obesity (associated or not with the presence of diabetes mellitus) determined significantly higher values of serum leptin in both genders." (PMID 32858998, 2020). "Leptin provides a link between obesity and the risk of CRC, it is a sensitive marker of obesity-induced hormonal aberrations and may be directly involved in CRC tumorigenesis." (PMID 32486076, 2020). "Many authors have lately addressed the contribution of leptin to cardiac remodeling in heart failure and the possible explanation of the obesity paradox by the influence of leptin on the metabolism, apoptosis, and remodeling of the extracellular matrix and on hypertrophy." (PMID 32121175, 2020). "This short isoform may play a significant role in the transport of leptin through the blood–brain-barrier (BBB) to the brain, and can contribute to the actions of leptin in obesity." (PMID 32839413, 2020). "Similarly, in HFD-induced male mice, increased circulating leptin and decreased testosterone and LH were observed together with decreased expression of leptin receptor, kisspeptin, and GnRH, indicating a role in obesity-induced male hypogonadism." (PMID 33088334, 2020). "In addition, leptin has been suggested as an intermediate link between obesity and breast or prostate cancer." (PMID 33304380, 2020). "As such, obesity or overweight is developed when leptin resistance occurs." (PMID 33322303, 2020). "Among these, only survival probability of KIRC patients could be impacted by gender and expression levels of four obesity-elated genes (LEP, MC4R, TMEM18, and PCSK1)." (PMID 33299884, 2020). "As well, very recent studies suggest that CRP is not only capable of binding to leptin but may compete with it for binding to the leptin receptor, which may lead to leptin resistance and, as a result, obesity." (PMID 32027700, 2020). "On the contrary, obesity is accompanied by an increased secretion of leptin." (PMID 32397353, 2020). "However, it is hard to draw any conclusions from the observations in rodent models for patients with diet-related obesity in the clinical setting, as obese patients normally display high circulating levels of leptin and are leptin resistant." (PMID 32655492, 2020). "Furthermore, L. sakei has been shown to ameliorate obesity and reduce the levels of biomarkers of obesity (e.g., leptin) in mice, and it can suppress pathologic bacterium, Corynebacterium tuberculostearicum, which induces chronic rhinosinusitis in human." (PMID 32799896, 2020). "There are several mechanisms by which obesity is believed to promote CRC, this includes increase in leptin levels that cause an increase in growth and proliferation of colon cancer cells, altered adipokine levels, altered gut microbiome apart from increased steroid hormones and growth factors." (PMID 32811441, 2020). "One potential explanation for this discrepancy is that leptin may have different effects in the context of lean compared to obese organisms due to chronic exposure to elevated leptin levels with obesity." (PMID 33170123, 2020). "The leptin–melanocortin pathway is commonly dysregulated in obesity." (PMID 32733386, 2020). "How does obesity amplify the actions of insulin (and leptin) on POMC neurons in males?" (PMID 32160920, 2020). "We next determined whether BAT Mettl3 expression was associated with obesity by measuring BAT Mettl3 expression in two obese mice models (high-fat diet-induced obese (DIO) and leptin-deficient ob/ob mice)." (PMID 32245957, 2020). "Leptin’s regulation of obesity-induced cardiac extracellular matrix remodeling." (PMID 32236321, 2020).
Obesity (continued). "In addition, the CNS group showed significantly reduced leptin levels (a serum obesity related hormone) as compared to HFD, NaCl, and GS groups (P < 0.05)." (PMID 32099024, 2020). "However, excessive fat deposition in obesity leads to an unbalanced adipokine expression in adipocytes, resulting in metabolic syndromes such as insulin/leptin resistance." (PMID 33218042, 2020). "Moreover, genetic manipulation of the UPR transcription factor spliced X-box binding protein (Xbp1) specifically in POMC neurons protects against diet-induced obesity and ameliorates leptin and insulin sensitivity." (PMID 32163401, 2020). "Moreover, as it has been already mentioned by other authors in the past, there is still an important gap in the physiological role of leptin independently of obesity condition." (PMID 33316927, 2020). "Leptin was shown to promote ILC2 and Th2 cytokine production in allergic airway disease, demonstrating that increased leptin levels associated with obesity could be driving the increased risk for allergy/asthma that is observed in obesity." (PMID 33584724, 2020). "Similarly, in boys with obesity, there was a higher expression of insulin (p <0.0001), leptin (p <0.0001), c-peptide (p < 0.0001), amylin (p = 0.0013), glucagon (p = 0.04), GLP-1 (p < 0.0001), and ghrelin (p = 0.07), compared to the eutrophic group." (PMID 33644105, 2020). "Leptin and adiponectin are constituent of adipocytokines and are produced from adipose tissue; therefore, regulation of these factors is important in the development of metabolic diseases including obesity." (PMID 32397362, 2020). "Leptin may also play a role in the progression of obesity, as it has been shown to be positively correlated with levels of adipose tissue; this is especially concerning since leptin is a pro-inflammatory factor in the body." (PMID 32742493, 2020). "This pathway is essential for the anti-obesity activity of leptin in the brain." (PMID 32731387, 2020). "However, a recent report demonstrating increased PDAC development in KC mice with genetic obesity (ob/ob mice), which lack leptin production, questions the importance of leptin in obesity-associated PDAC." (PMID 32709161, 2020). "LEP is one of the major appetite regulation factors in mammals and causes mouse obesity when LEP is absent." (PMID 32727133, 2020). "Besides poor eating habits, especially excess calorie intake, leptin and adiponectin are important variables that influence excessive weight and obesity." (PMID 31252598, 2019). "Leptin protein content in SAT was also increased in individuals with obesity." (PMID 31533725, 2019). "According to the previous reports, during pregnancy and also in some forms of obesity, inhibited transport of leptin across the blood-brain barrier may lead to leptin resistance." (PMID 31975995, 2019). "However, in case of obesity the secreted adipokines take on a more proinflammatory profile, secreting IL-6, TNFα and leptin, as well as resistin and visfatin." (PMID 30787925, 2019). "The hypothalamic negative effects could compensate the peripheral and positive ones that predominate only when central leptin resistance occurs with obesity onset or else when the serum leptin level rises above a certain threshold." (PMID 31500090, 2019). "Absence of leptin signaling in early life alters the energy balance and predisposes the animals to obesity." (PMID 30694175, 2019). "Furthermore, leptin, that is a cytokine overexpressed in obesity, represented the best predictor of behavioral differences between groups in both tasks." (PMID 31664059, 2019). "This study was aimed to provide further data on intestinal permeability (IP), IEC repair, intestinal leptin/ObR-b binding and microbiota during AP attack to clarify that obesity may aggravate pancreatic injury through IMB dysfunction." (PMID 30635594, 2019). "The multifaceted role of the obesity adipokine leptin in this respect is also discussed." (PMID 30634494, 2019).
Obesity (continued). "Obesity is accompanied by increased leptin concentration in plasma." (PMID 30832310, 2019). "Given that many biological actions of leptin are mediated by NO, we aimed to evaluate if a functional relationship among them in liver inflammation and fibrosis in the context of obesity." (PMID 30818874, 2019). "Leptin is produced by adipose tissue and its levels are increased in obesity." (PMID 31207998, 2019). "By studying the interactions between increased loading and other known systems affecting BW, such as the FGF system and leptin, we may identify novel targets for anti-obesity treatment." (PMID 30888399, 2019). "Altogether, considering the reduction effect of PD in adipose tissue mass and body weight in HFD-fed mice, our results indicate that PD is involved in regulation of leptin expression in obesity and thus might affect body weight." (PMID 31828124, 2019). "Leptin is a fundamental peripheral hormone that, increasing after each meal, induces the feeling of satiety in the brain; its expression and secretion rise in obesity." (PMID 31619003, 2019). "This raises the exciting possibility that, using low leptin levels as a biomarker, a leptin analog or other receptor agonist might be developed as a therapeutic for a subset of patients with obesity." (PMID 30357355, 2019). "This may be less true for accruing morphological characters like obesity, where adipose mass probably reflects complex, long-term leptin-diet relationships, leptin resistance and feedback." (PMID 31661517, 2019). "Furthermore, four parameters (weight, Lee’s obesity index, serum leptin, and adiponectin levels) were analyzed for correlation with gut microbiota." (PMID 31117266, 2019). "Our results therefore support an established relationship between obesity and the microbiome and, furthermore, allow us to generate novel hypotheses about leptin-dependent detection of CD4 +T cell interaction with the microbiome." (PMID 31882682, 2019). "Reduced sensitivity to leptin, an adipokine reported to have a pathophysiological role in PH, in obese patients may account for the protective effect of obesity." (PMID 30689673, 2019). "However, leptin resistance observed in obese individuals potentially disqualifies leptin therapies as a cure to the obesity and type 2 diabetes epidemic." (PMID 31620009, 2019). "Even both cytokines are secreted by adipose tissue and are involved in inflammation pathways, the salivary level of leptin was not correlated with the IL-6 level (r = 0.07, P = 0.41), six cases of obesity were characterized by elevated IL-6 and normal level of salivary leptin." (PMID 30605486, 2019). "To indicate whether the leptin and adiponectin signaling pathways influence the antiobesity effects of PSE, we used HFD to induce obesity in obese mice for one month and transferred leptin, adiponectin, and leptin plus adiponectin gene in obese mice in vivo." (PMID 31737168, 2019). "Moreover, melatonin was effective in decreasing the levels of leptin and resistin in plasma of animals induced to obesity by an HFD." (PMID 31489938, 2019). "The leptin deficient mice (ob/ob mice) exhibited hyperphagia, obesity and insulin resistance, while the administration of leptin in leptin lacking mice reverses these alterations." (PMID 31736870, 2019). "In conclusion, we suggest that aberrant performance of individuals affected by obesity in temporal tasks might be, at least in part, explained by the serum level of pro-inflammatory marker of leptin." (PMID 31664059, 2019). "However, the role of leptin in maintaining energy balance is asymmetric; low levels strongly promote restoration of fat stores, whereas high levels weakly resist obesity." (PMID 31245374, 2019). "Leptin plays essential roles in the regulation of the mass of adipose tissue and body weight, and lack of leptin causes obesity." (PMID 31185614, 2019).
Obesity (continued). "The authors proposed that this apparent paradoxical finding could be explained by the leptin resistance condition in obesity, in which leptin may partially lose its ability to downregulate FNDC5." (PMID 31404407, 2019). "Previous research has shown that leptin can improve metabolism in ob/ob mice prone to obesity." (PMID 31022919, 2019). "Since leptin is an adipokine that is generally recognized as representing adipose tissue mass while BMI cannot differentiate between fat and lean muscle mass, measurement by waist circumference is most relevant to obesity." (PMID 31236292, 2019). "Leptin, an adipokine correlated with adipose tissue mass, is elevated in people with obesity and obese mice, an observation confirmed in the current study, and may play a cancer promoting role in obesity-related cancers." (PMID 31835454, 2019). "It has been suggested that adipokines, such as leptin and visfatin, could represent a pathomechanistic link in the interactions between periodontitis and obesity." (PMID 30609928, 2019). "In the future, leptin concentrations could be analyzed based on BMI percentile stratifications to explore relationship to obesity among children with ASD." (PMID 31277383, 2019). "Accumulating evidence has shown gastric leptin to perform diverse functions, such as those in nutrient absorption and carcinogenesis in the gastrointestinal system, independent of its well-known role in appetite regulation and obesity." (PMID 31141984, 2019). "As the leptin concentration increases, appetite and adipogenesis both increase, whereas the increase in adiponectin concentration increases insulin sensitivity and lipolysis, thereby improving obesity." (PMID 31137884, 2019). "However, it was soon realized that individuals with obesity are refractory to the appetite suppressing and weight lowering effects of exogenous leptin treatment." (PMID 31225498, 2019). "Leptin in particular is greatly increased in obesity, and has a stimulatory effect on the SNS; therefore, it is highly likely that leptin may be one driver of SNS overactivity in obesity." (PMID 30747398, 2019). "An excess of pro-inflammatory adipokines (leptin, TNF-α, IL-6, etc.)may be responsible for the association between asthma and obesity." (PMID 31842862, 2019). "It is therefore speculated that for people with poor SRH, obesity accompanied by elevated leptin concentration and leptin resistance may contribute to some extent the subsequent cardiovascular risk." (PMID 31832026, 2019). "Our laboratory has revealed that obese rats induced by an high-unsaturated fat diet (20% fat) show an increase of vascular L-arginine/NO pathway in order to protect the integrity of vascular function in obesity, possibly mediated by elevated levels of plasma leptin." (PMID 30949067, 2019). "The lack of leptin in ob/ob mice results in strong hyperphagia underlying development of obesity even on a standard diet." (PMID 31878078, 2019). "Leptin, a main regulator of energy balance, has a key preventive role of obesity during lactation." (PMID 31661820, 2019). "Although leptin is the hallmark of obesity and a major appetite suppressant, no effective obesity therapy based on this hormone has been developed." (PMID 31717265, 2019). "In the current study, targeted resequencing of the coding regions of 31 selected genes known to be involved in monogenic forms of obesity (excluding LEP, LEPR and MC4R) was performed in 23 probands from Pakistani families with severe early-onset obesity segregating as an autosomal recessive trait." (PMID 31488071, 2019). "In recent years, new strategies have been developed to recover the response to leptin in obesity." (PMID 31717265, 2019). "Leptin induces satiety, and thus, a lack of functional leptin in these animals causes hyperphagia and subsequent obesity." (PMID 30823474, 2019).
Obesity (continued). "Also, transgenerational inheritance of obesity consistent with a leptin resistant was reported to be induced by transgenerational epigenetic programming of DNA methylome in adipose tissue." (PMID 31849831, 2019). "Therefore, the establishment of leptin resistance is considered as a major mechanism linking to the onset of obesity." (PMID 30680172, 2019). "In addition, Gogas and colleagues suggest a possible role in melanoma development of high circulating levels of leptin, a factor involved in glucose metabolism and directly related with obesity, insulin levels and female sex." (PMID 31547443, 2019). "Converging lines of evidence have demonstrated that leptin exerts a regulatory role in the connection between energy metabolism and the immune system, being a crucial adipokine responsible for the inflammatory state found in obesity." (PMID 30818874, 2019). "HFD induced obesity, metabolic impairment, and high serum and fat leptin levels." (PMID 31616626, 2019). "Although the primary function of the protein leptin has generally been viewed as promoting leanness, by signaling back to the CNS to decrease intake of food and increase energy expenditure to limit obesity, the overall role of leptin is far more complex and to date remains somewhat elusive." (PMID 31555578, 2019). "We show that the resulting reduction in hepatic lipid content occurs independently of differences in body weight and calorie intake, and we provide evidence that leptin action on liver lipid metabolism is preserved in obesity when leptin is delivered directly into the CNS." (PMID 31222048, 2019). "A proteomic study conducted in adipose tissue of leptin-deficient (ob/ob) mice treated with leptin recognized PRDX6 as one among 12 functional proteins that by regulating mitochondrial physiology and oxidative stress were implicated in obesity mechanisms." (PMID 31949886, 2019). "Moreover, leptin, the circulating levels of which are increased in obesity, further inhibits testosterone production by Leydig cells." (PMID 31109063, 2019). "It is a 16kDa non-glycosylated protein encoded by the LEP (ob) gene, involved in appetite and obesity regulation by the induction of anorexigenic factors and suppression of orexigenic neuropeptides." (PMID 31443349, 2019). "The results further confirmed our hypothesis that sleep duration modifies the effect of GPSleptin on obesity to a degree via the leptin pathway." (PMID 31285522, 2019). "Leptin, a 16 kDa non-glycosylated protein encoded by the obese (ob) gene, is mainly secreted by adipose tissue and regulates appetite and obesity by inducing anorexigenic factors and suppressing orexigenic neuropeptides." (PMID 30917508, 2019). "Moreover, a recent study has demonstrated that obesity reduces the level of the tumor suppressor p16INK4A protein in breast adipocytes, which in turn seems to upregulate leptin expression at mRNA level to promote also procarcinogenic processes." (PMID 31380268, 2019). "These may in turn override the NE-HPA suppressive effects of leptin promoting development of obesity in this polygenically obese model." (PMID 30886140, 2019). "This study presents the first evidence that HFD consumption does not necessarily induce an obesity-associated protumorigenic environment in the stomach that is accelerated by HFDs, actively stimulating gastric leptin production." (PMID 31489936, 2019). "Accordingly, we speculate that leptin may act as a combined bridge between psoriasis and obesity through inflammatory processes." (PMID 31521168, 2019). "Importantly, insulin resistance is induced by obesity–leptin resistance, which activates the inflammatory mitogen-activated protein kinase (MAPK) pathway." (PMID 31052312, 2019). "Besides, it was first reported that proopiomelanocortin (POMC)–specific ablation of Mfn2 results in endoplasmic reticulum (ER) stress–induced leptin resistance and decreased energy expenditure for protection against obesity." (PMID 31551926, 2019).